CTSD (cathepsin D)
Diseases named in the same sentence as CTSD in open-access papers (continued):
Sharing a sentence is not in itself a finding about the gene and the disease.
uveal melanoma (2 papers, 2019 to 2020). A melanoma derived from melanocytes of the uveal tract. "Other studies showed higher levels of cathepsin D and gp100 in sera of patients with uveal melanoma compared to healthy volunteers’ sera." (PMID 31086060, 2019). "Analogous analyses of sera from uveal melanoma patients and healthy control revealed, based on different spot sizes, a differential expression of gp100 and cathepsin D that were later investigated as possible melanoma biomarkers." (PMID 31086060, 2019). "In addition, cathepsin D has been identified as a potential biomarker in uveal melanoma using an unbiased proteomics approach." (PMID 33147716, 2020).
abscess (1 paper, 2025). An inflammatory process characterized by the accumulation of pus within a newly formed tissue cavity which is the result of a bacterial, fungal, or parasitic infection or the presence of a foreign body. "This, together with previous data took us to analyse the levels of Cathepsin D in the inflamed abscess from the paws of Pik3caRBD/– and Pik3caWT/– mice." (PMID 40272400, 2025).
adenoma (1 paper, 2021). A neoplasm arising from the epithelium. "This aligns with previous work showing that mRNA levels of CTSB and CTSD increase concurrently with APC gene mutations that initiate the adenoma-adenocarcinoma sequence." (PMID 34428252, 2021).
allergic rhinitis (1 paper, 2025). Inflammation of the nasal mucous membranes caused by an IgE-mediated response to external allergens. "The proteins ORM, APOH, FGA, CTSD, and SERPINB3, which showed promise in preclinical studies for predicting response to glucocorticoids, have also been evaluated in clinical trials involving patients with seasonal allergic rhinitis (SAR)." (PMID 40551926, 2025).
Anxiety (1 paper, 2022). Intense feelings of nervousness, tension, or panic often arise in response to interpersonal stresses. "Mice heterozygous for cathepsin D deficiency (CTSD) manifest reduced anxiety-like behavior." (PMID 36614124, 2022).
Ataxia (1 paper, 2025). Ataxia refers to impaired coordination of voluntary muscle movement. "Patients with significantly reduced Cathepsin D activity presented with ataxia and progressive psychomotor retardation." (PMID 39823474, 2025).
attention deficit-hyperactivity disorder (1 paper, 2020). A disorder characterized by a marked pattern of inattention and/or hyperactivity-impulsivity that is inconsistent with developmental level and clearly interferes with functioning in at least two settings (e.g. at home and at school). "In two distinct studies, CTSD knockout mice exhibited hyperactivity, a hallmark of attention deficit hyperactivity disorder (ADHD) and mania." (PMID 32793006, 2020).
behavioral disorders (1 paper, 2022). "In adults with nonspecific mental, motor, or behavioral disorders, in whom NCL is suspected, the first line of testing includes the just-mentioned enzymatic tests for PPT1, TTP1, CTSD, and CTSF, which, when normal, should prompt the clinician to perform ultrastructural testing." (PMID 35628533, 2022).
Blindness (1 paper, 2022). Blindness is the condition of lacking visual perception defined as a profound reduction in visual perception. "The specificity of VHH‐B9 for BACE1 also avoids issues of impaired glucose homeostasis, hypopigmentation, seizures, and blindness (among others), which are associated with cross‐reactivity with BACE2, Cathepsin D, and Cathepsin E." (PMID 35352880, 2022).
brain glioma (1 paper, 2020). A malignant glioma that involves the brain. "Additionally, cathepsin D (CTSD) with four agents-treated brain glioma sections, were stained to validate whether APZ inhibits lysosomal integrity leading to autophagic cell death in the orthotropic xenograft model." (PMID 32120820, 2020).
Cachexia (1 paper, 2010). Severe weight loss, wasting of muscle, loss of appetite, and general debility related to a chronic disease. "Increased cathepsin D and acid phosphatase activity has been demonstrated in patients with varying tumor types and degrees of weight loss, suggesting that increased lysosomal activity may contribute to the development of cachexia." (PMID 20193046, 2010).
cataract (1 paper, 2017). Partial or complete opacity of the crystalline lens of one or both eyes that decreases visual acuity and eventually results in blindness. "Compared with the cataract group, the levels of cathepsin D (P < 0.001), sNCAM (P < 0.001) and sVCAM-1 (P = 0.007) were significantly higher in the aqueous humour samples from POAG." (PMID 29183303, 2017).
Cerebellar atrophy (1 paper, 2021). Cerebellar atrophy is defined as a cerebellum with initially normal structures, in a posterior fossa with normal size, which displays enlarged fissures (interfolial spaces) in comparison to the foliae secondary to loss of tissue. "Significant loss of cathepsin D enzymatic function due to the CTSD gene heterozygous missense mutations is associated with childhood motor and visual disturbances, cerebral and cerebellar atrophy, as well as progressive psychomotor disability." (PMID 34198733, 2021).
Cerebral atrophy (1 paper, 2025). Atrophy (wasting, decrease in size of cells or tissue) affecting the cerebrum. "Serum cathepsin D levels have been associated with AD dementia and cerebral atrophy, suggesting the potential of cathepsin D as a prognostic biomarker of global cognitive and functional decline." (PMID 40869205, 2025).
cerebral small vessel disease (1 paper, 2025). Cerebral small vessel disease is the term currently used to pathological processes that affect the brain parenchymal circulation (arterioles, capillaries, and veins). "In cerebral small vessel disease (CSVD), proteomic analyses revealed that CD56 dim NK cells may contribute to BBB breakdown through secretion of cathepsin D (CTSD), a molecule that participates in protein degradation." (PMID 41403931, 2025).
Chagas disease (1 paper, 2023). A parasitic infection caused by Trypanosoma cruzi. "Here, we investigate the functional role of the oocyte maternally accumulated mRNAs of a protein phosphatase (PP501) and two aspartic proteases (cathepsin-D 405, CD405 and cathepsin-D 352, CD352) in the yolk degradation and reproduction of the insect vector of Chagas disease Rhodnius prolixus." (PMID 36923285, 2023).
Cirrhosis (1 paper, 2021). A chronic disorder of the liver in which liver tissue becomes scarred and is partially replaced by regenerative nodules and fibrotic tissue resulting in loss of liver function. "Moreover, compared with healthy controls, the concentration of plasma Cathepsin D was as much as 10 times higher in patients with various liver diseases such as cirrhosis, primary hepatoma, hepatitis infection, or hepatocarcinoma." (PMID 33669204, 2021).
cognitive decline (1 paper, 2025). "CLN10 is caused by dysfunction of Cathepsin D (CTSD), leading to progressive cognitive decline, loss of speech, visual dysfunction, and motor function loss." (PMID 39925015, 2025).
cyst (1 paper, 2022). A sac-like closed membranous structure that may be empty or contain fluid or amorphous material. "Autophagy-dependent cell death was excluded; however, lysosomal factors such as Cathepsin D, deep orange, and Carnation were shown to be involved, although it was not indicated in which cell type, i.e., the cyst or germ cells, they functioned." (PMID 35714186, 2022).
delirium (1 paper, 2023). A disorder characterized by confusion; inattentiveness; disorientation; illusions; hallucinations; agitation; and in some instances autonomic nervous system overactivity. "We observe decreased levels in three proteases (CTSV, CTSD and MMP14) in the CSF of patients that will develop delirium." (PMID 37759795, 2023).
diabetic nephropathy (1 paper, 2023). "Other proteins found with an altered abundance in our study and known to be related to diabetic nephropathy are CTSD, FHL2, and Sec31A." (PMID 36769128, 2023).
dyslipidaemia (1 paper, 2021). "The current study establishes a key role for extracellular CTSD in NASH-induced dyslipidaemia." (PMID 34335574, 2021).
endophthalmitis (1 paper, 2023). An infectious process affecting the internal structures of the eye. "This study found that Annexin A5, cathepsin D, and C5a were significantly downregulated in infected mice compared to uninfected mice, indicating their potential as prospective biomarkers for the diagnosis or prognosis of Staphylococcus aureus endophthalmitis." (PMID 37603522, 2023).
gouty arthritis (1 paper, 2025). "This further suggests that exosomes, via intercellular communication, influence the expression of HPRT1 and CTSD proteins in recipient cells, participating in the development and progression of gouty arthritis." (PMID 40508129, 2025). "This suggests that the HPRT1 and CTSD proteins are key targets involved in the development of gouty arthritis, see." (PMID 40508129, 2025). "Exosome co-culture experiments have confirmed that exosomes derived from the plasma of rats with gouty arthritis can induce upregulation of CTSD in NRK cells, indicating the critical role of exosomes in transmitting signals of lysosomal dysfunction." (PMID 40508129, 2025).
head and neck cancer (1 paper, 2024). A primary or metastatic malignant neoplasm affecting the head and neck. "We then hypothesised that the 5 upregulated genes (namely, ATPase phospholipid transporting 8A1 [ATP8A1], BAHD1, cathepsin [CTSD], janus kinase 1 [JAK1], and myosin regulatory light chain interacting protein [MYLIP]) play a role in radioresistance of prostate and head and neck cancers." (PMID 39719436, 2024).
hepatitis C (1 paper, 2011). "Cathepsin D (CTSD), a lysosomal aspartyl protease associated withseveral disease processes, was significantly upregulated in the ENCODE arrayanalysis of 5′ capped RNA from hepatitis C cirrhotic liver (fold increase 1.9,p<0.001)." (PMID 21359205, 2011).
herpes zoster (1 paper, 2024). A common dermal and neurologic disorder caused by reactivation of the varicella-zoster virus that has remained dormant within dorsal root ganglia, often for decades, after the patient's initial exposure to the virus in the form of varicella (chickenpox). "These include elevated levels of cathepsin D and IL-18, which are associated with reduced risk of herpes zoster, as well as increased risk of postherpetic neuralgia with elevated levels of Ficolin-3 and IL-2 receptor α." (PMID 39253091, 2024). "However, elevation in cathepsin D (OR: 0.6807, 95% CI: 0.4638-0.9991, PIVW: 0.0495) and IL-18 (OR: 0.6845, 95% CI: 0.4715-0.9939, PIVW: 0.0464) was associated with a decreased risk of herpes zoster." (PMID 39253091, 2024).
infarction (1 paper, 2020). A localised pathological necrosis of tissue resulting from obstruction of the blood supply usually by a thrombus, an embolus, or vascular torsion. "Cathepsin D plays a role in cardiomyocyte autophagy, which protects against the progression of post-infarction cardiac remodeling." (PMID 33256720, 2020).
infertile (1 paper, 2015). "In our previous study, random distribution and depletion of H3K9ac interaction in many loci (for example, CTSD, FLNA, MCF2L, PLXNA3, SG3GLB2, TH) of infertile men sperm have been confirmed." (PMID 25806092, 2015).
influenza (1 paper, 2016). An acute viral infection of the respiratory tract, occurring in isolated cases, in epidemics, or in pandemics; it is caused by serologically different strains of viruses (influenzaviruses) designated A, B, and C, has a 3-day incubation period, and usually lasts for 3 to 10 days. "Of the proteins with reduced expression identified in our study, the five most-reduced DEPs in samples from influenza-infected patients that were also correlated with higher viral loads were CTSD, KLK7, MFGE8, MAPK9 and CD27, respectively." (PMID 27088501, 2016).
invasive ductal carcinomas of (1 paper, 1998). "We also assessed the association between cathepsin D expression and histomorphological tumour subtypes (invasive ductal carcinoma with extensive intraductal component, multifocal tumour)." (PMID 9683294, 1998).
lactic acidosis (1 paper, 2024). Metabolic acidosis characterized by the accumulation of lactate in the body. "Previous studies showed that cathepsin D is released more in acidic environments, suggesting an association with septic shock with lactic acidosis." (PMID 39767696, 2024).
large cell neuroendocrine lung carcinoma (1 paper, 2006). "Remarkably, small cell lung carcinoma (SCLC) and large cell neuroendocrine lung carcinoma (LCNEC) displayed distinctive cathepsin D expression that was limited to the stromal cell compartment with little or no tumor cell staining." (PMID 17183660, 2006).
lymphopenia (1 paper, 2020). Reduction in the number of lymphocytes. "In contrast, CTSD-deficient (CTSD-/-) mice develop normally for 2 weeks after birth but die with intestinal necrosis, thromboembolism, and lymphopenia within 4 weeks." (PMID 32176724, 2020).
malignant glioma (1 paper, 2021). A grade III or grade IV glioma arising from the central nervous system. "Mass spectrometry analysis showed that CTSD was important in the invasiveness of malignant glioma cells and increased CTSD expression correlates with more advanced GBM grade and poorer survival." (PMID 34062746, 2021).
medulloblastoma (1 paper, 2024). A malignant, invasive embryonal neoplasm arising from the cerebellum. "In addition, miR-204 downregulates M6PR, IGF2R genes involved in the lysosomal segregation of cathepsin B and cathepsin D lysosomal enzymes in medulloblastoma cells." (PMID 38611021, 2024).
membranous nephropathy (1 paper, 2023). "Cathepsin D was also found to be upregulated in membranous nephropathy, another immune-mediated kidney disease." (PMID 37071647, 2023).
memory impairment (1 paper, 2022). "The higher serum Cathepsin D, IgE, EGFR, MMP-9, vWF, haptoglobin, and p-Tau181 levels were associated with severity of memory impairment (as indicated by lower MMSE and MoCA scores, and higher ADL, CDRglobal, and CDRsob scores)." (PMID 35769604, 2022).
myoclonic epilepsy (1 paper, 2021). A group of epilepsy syndromes in which myoclonic seizures are a prominent feature. "As the only variant that was ClinVar-annotated as pathogenic, the CTSD variant was reported previously as a homozygous change in two siblings with myoclonic epilepsy, respiratory failure CTSD deficiency." (PMID 34070492, 2021).
neuroendocrine tumor (1 paper, 2006). "We first assessed migration of prostate neuroendocrine tumor cells derived form CR2-TAg mouse tumors (PNEC cells,), in 3D matrigel co-cultures with wt (CTSD+/+) or cathepsin D-deficient (CTSD−/−) fibroblasts." (PMID 17183660, 2006).
neuropathies (1 paper, 2020). "It is not yet clear how CTSD deficiency causes neuropathies; however, experimental evidence suggests defective autophagy might be in part responsible, as CTSD is essential in degrading cellular components during macroautophagy." (PMID 32326609, 2020).
Niemann-Pick disease (1 paper, 2014). A group of inherited, severe metabolic disorders in which sphingomyelin accumulates in lysosomes in cells. "Mutations in the CTSD gene are involved in the pathogenesis of AD and Niemann–Pick disease." (PMID 25295026, 2014).
parasite (1 paper, 2020). "Here, the significantly upregulated expression of cathepsin L (6.38 fold) and cathepsin D (15.49 fold) in the infected bryozoans suggested an increased probability of reducing parasite infection in bryozoans." (PMID 32824626, 2020).
parasitemia (1 paper, 2011). "Proportion and numbers of DC subsets in the spleen were similar in both WT and cathepsin D in deficient mice at peak parasitemia." (PMID 22053177, 2011). "However later in infection, the cathepsin D deficient mice showed a reduced parasitemia." (PMID 22053177, 2011).
peripheral vascular disease (1 paper, 2022). Any disorder affecting blood flow through the veins or arteries outside of the heart. "Furthermore, an independent relationship was confirmed by the multivariable-adjusted linear regression model between baPWV and two biomarkers—hsTnT and Cathepsin D—indicating the link between peripheral vascular disease evaluation and proteins from cardiac origin." (PMID 35455752, 2022).
pneumococcal pneumonia (1 paper, 2011). A febrile disease caused by STREPTOCOCCUS PNEUMONIAE. "Moreover mice reconstituted with cathepsin D−/− bone marrow have significant impairment in their capacity to clear pneumococci from the lung and recruit greater numbers of neutrophils, the central pathologic feature of pneumococcal pneumonia." (PMID 21298030, 2011). "Preliminary data showed cathepsin D−/− BMDM produced higher levels of KC and MIP-2 than WT BMDM, 16 h after bacterial exposure, consistent with a role for these chemokines in neutrophil recruitment in other models of pneumococcal pneumonia (data not shown)." (PMID 21298030, 2011).
Primary immunodeficiency (1 paper, 2024). "For instance, CTSD is involved in the pathways of ‘Notch signaling pathway,’ CEBPD and CYP27A1 simultaneously mediate ‘T cell receptor signaling pathway,’ ‘Primary immunodeficiency’ and ‘bacterial infection’ signal pathways." (PMID 38451044, 2024).
pulmonary fibrosis (1 paper, 2022). Chronic progressive interstitial lung disorder characterized by the replacement of the lung tissue by connective tissue, leading to progressive dyspnea, respiratory failure, or right heart failure. "Moreover, patients with pulmonary fibrosis and inflammation, including those with CF, showed increased levels of cathepsin D." (PMID 35097122, 2022).
Renal cyst (1 paper, 2023). A fluid filled sac in the kidney. "CTSD expression was also significantly upregulated in renal cysts compared with normal human renal tubules and correlated with renal cystic epithelial cell nuclear TFEB staining." (PMID 36794754, 2023).
Retinal dystrophy (1 paper, 2021). Retinal dystrophy is an abnormality of the retina associated with a hereditary process. "Results demonstrate that cathepsin D deficiency results in an early-onset and rapidly progressing retinal dystrophy that involves all retinal cell types." (PMID 33800998, 2021). "In the present study, we performed a detailed analysis of the retinal dystrophy in Ctsd ko mice to obtain insights into the pathological alterations associated with CTSD deficiency." (PMID 33800998, 2021). "Data on the progression of the retinal dystrophy, the different retinal cell types affected by the cathepsin D deficiency, and the molecular changes associated with the severe retinal pathology in this animal model are, however, limited." (PMID 33800998, 2021).
rheumatoid arthritis (1 paper, 2022). A chronic, systemic autoimmune disorder characterized by inflammation in the synovial membranes and articular surfaces. "Another cathepsin which can serve its role in rheumatoid arthritis includes Cathepsin D. Cathepsin D is abundantly produced via chondrocytes and exert its enhanced activity in rheumatoid arthritis." (PMID 35002435, 2022).
sarcoma (1 paper, 2015). A usually aggressive malignant neoplasm of the soft tissue or bone. "Immunoblotting analysis proved that CTSD was over-expressed in sarcomas (p < 0.0083) and pulmonary metastases (p = 0.0061) compared to fetal osteoblasts, thus confirming the 2-DE data." (PMID 26203049, 2015). "In contrast to RANBP1, CTSD was increased on the protein level in the sarcoma and metastatic cell lines with its highest expression in the sarcoma cell lines." (PMID 26203049, 2015).
senile cataract (1 paper, 2017). A cataract with no obvious cause occurring in persons over 50 years old. "Compared with the senile cataract group, the concentrations of cathepsin D, sNCAM and sVCAM-1 were significantly higher in AH samples from POAG (all P < 0.05)." (PMID 29183303, 2017).
tongue SCC (1 paper, 2018). "We have previously reported the expression of cathepsin B and cathepsin D by CSC subpopulations within oral tongue SCC and IDHWGB, suggesting the presence of bypass loops for the RAS." (PMID 30177970, 2018).